MIR6834 (microRNA 6834)
Synonyms: hsa-mir-6834
Gene: MicroRNA gene on chromosome 6 (33,290,245 to 33,290,325, forward strand). Ensembl gene ENSG00000284064.
Homologues: Orthologues: chimpanzee MIR6834 (100% identical).